CD86 (CD86 molecule)
Diseases named in the same sentence as CD86 in open-access papers (continued):
Sharing a sentence is not in itself a finding about the gene and the disease.
tumor (continued). "The number of nuclei exhibiting positive staining with DAPI (blue) was designated as total cells, and CD68 (Cy3 red fluorescence) + CD86/CD163 (FITC green fluorescence) double fluorescent staining was utilized to label tumor-associated macrophages." (PMID 39531417, 2024). "Western blotting assay further confirmed the presence of typical M1-like macrophage markers, including CD86 and iNOS, along with tumor-targeting associated proteins such as α4β1 integrins, on the surface of BC@Z-M." (PMID 39613774, 2024). "Our retrospective clinical study investigated the association between CD80, CD86, and PD-L1 expression, tumor characteristics, prognostic factors, and survival in cutaneous malignant melanoma." (PMID 37614091, 2024). "Concomitantly, HLA augmented the expression of other M1-associated markers including CD40 and CD86, which further supports that HLA shifted macrophages to anti-tumor phenotypes." (PMID 38191648, 2024). "These can transform either into M1 and M2 types, whereby the former exhibit antitumour properties and express abundant CD86, while the latter are associated with tumour progression and express high levels of CD206." (PMID 36693064, 2023). "It has been reported that the loss expression of CD86, which was implicated in controlling tumor growth, was associated with decreased tumor-infiltrating T lymphocytes (T-TILs) in DLBCL patients." (PMID 37234150, 2023). "HRS cells and some tumor-associated macrophages (TAMs) are also positive for CD86, the CTLA-4 ligand, suggesting a role for the CTLA-4/CD86 axis in contributing to immune evasion." (PMID 37760478, 2023). "Our results indicate that B-LNP treatments induced TAMC expression of co-stimulatory factors (CD40, CD80, CD86) and enhanced tumor-associated antigen presentation, and, importantly, impaired TAMC immunosuppressive activities." (PMID 36959214, 2023). "An antibiotic cocktail (ABX) reduced the number of CD11chigh MHC‐IIhigh DCs as well as CD86 expression and IL‐12B production in tumour‐associated DCs, diminishing the efficacy of CpG‐ODN therapy." (PMID 38082435, 2023). "The FBZ-treated EL-4 cells expressed higher levels of PD-L1 and CD86, which are associated with T cell immunity in the tumor microenvironment (TME), than the controls." (PMID 37998737, 2023). "Enhanced uptake of the CDN nanocarriers was associated with an increased proportion of activated Ag+CD86+ DCs compared with untreated or liposome-CDN treated tumours." (PMID 35606429, 2022). "The tumor resection procedure causes a dramatic and immediate inflammatory response at the tumor resection site, accompanied by upregulation of the CD86 marker." (PMID 35884700, 2022). "Melanoma cell-derived EVs carrying tumor-associated antigens (TAAs) promote DCs to express maturation marker CD86 and raise the anti-tumor activity in mouse models." (PMID 36405712, 2022). "The results showed that CD58 expression was positively linked to the monocyte marker CD86, neutrophil markers CD66b and CD11b, tumor-associated macrophage (TAM) marker CD68." (PMID 34193136, 2021). "The second-highest correlation was found between SLC1A5 expression and CD86, a marker gene of tumor-associated macrophages with the ability to capture PD1-targeting antibodies on its surface and consequently limiting immunotherapeutic efficacy." (PMID 34367941, 2021). "CD86+ B cells were associated with higher tumour grade and a greater number of metastatic lymph nodes." (PMID 34141724, 2021). "In summary, CD86 expression is associated with tumor progression and prognosis for LGG patients, where its prognostic value was observed to be independent of clinical features." (PMID 33954112, 2021). "The abundances of immune cells, which delivered pro-tumor suppression (including macrophages, myeloid-derived suppressor cells (MDSCs), and regulatory T cells), were positively associated with CD86 expressions in patients with BC." (PMID 34422632, 2021).
tumor (continued). "In this study, we generated CD80/CD86-targeted CAR T cells to destroy CD80/CD86-associated tumor cells in culture and in the tumor xenograft mouse models." (PMID 33868277, 2021). "Regarding inter‐DCs’ analyses, CD86 expression on tumor‐infiltrating pDCs and cDC2s upon TLR triggering was linked together, similarly impacting clinical evolution." (PMID 33282290, 2020). "We found increased expression of CD86 on tumor-associated, vaccine-derived Stat3∆/∆ CD103+ cDC1s compared to Stat3fl/fl CD103+ cDC1s, as judged by relative CD86 amounts on CD45.2+ CD103+ cDC1s." (PMID 31947933, 2020). "After blockade of IL-4, the down-regulation of M1-associated cytokines (CXCL10, CD86, and IL-12) was observed as compared to cryo-thermal eosinophils + tumour-bearing macrophage group." (PMID 31519961, 2019). "CTLA-4 integrates with the costimulatory molecules CD80 (B7-1) and CD86 (B7-2) that express on the surfaces of APCs, while PD-L1 is expressed on a wide variety of cell types, including tumor-associated fibroblasts, tumor cells, APCs, etc.." (PMID 30774597, 2019). "This method has been used to deliver a combination of OX40L, CD80, and CD86 encoding mRNAs in different subcutaneous two-tumor models, where only one tumor was treated." (PMID 31878087, 2019). "Due to activated tumor-associated CD11c+DCs, which higher expression of CD86, we further evaluated the expression of tumor-associated CD86+DCs (CD45+CD11b+CD11c+CD86+) within the tumor tissue by flow cytometry." (PMID 30873170, 2019). "The statistical analysis also evidenced an association between higher CD86 mRNA levels and tumor size." (PMID 30123257, 2018). "In tumour-bearing mice, an increased number of B cells in the spleen is associated with cancer regression and the presence of B220+/CD86+ activated antigen-presenting B cells in the lymphoid organs and in the periphery." (PMID 28629331, 2017). "As Nrp1-dependent pathways can play a role in the behavior of tumor-associated macrophages in the periphery, we examined the phenotypic state of the GAMs by assessing them for expression of CD86, CD206, and TSPO, which are markers of inflammatory status." (PMID 26755653, 2016). "We found that GPC3 expression in the tumor increased F4/80+CD86+ macrophage (M1) proportion and caused GPC3-specific CD8+ T cell immune responses, and prolonged mouse survival." (PMID 24992906, 2014). "In addition, MAP1LC3C correlates with tumor-cell associated CD80 and CD86, cell costimulatory surface proteins that are primarily expressed on antigen-presenting cells (APCs) and tumor cells." (PMID 39928678, 2025). "Finally, we demonstrated that blockade of CD80 and CD86 improved the response to radiation, associated with decreased Treg in the tumor." (PMID 41417245, 2025). "CD86 expression is found on tumor-associated macrophages and dendritic cells; by modulating the function of these cells, CD86 influences the composition of the tumor microenvironment, thereby potentially promoting or suppressing tumor development." (PMID 41006647, 2025). "Ipilimumab is a monoclonal antibody against cytotoxic T lymphocyte antigen-4 (CTLA-4), which is known to inhibit binding of CD80 and CD86 molecules on antigen-presenting cells, thereby causing proliferation and activation of T cells and promoting presentation of tumor antigen." (PMID 38187173, 2024). "Furthermore, the CTLA-4/CD80, CD86 axis established between immune cells and tumor cells has been implicated in attenuating anti-tumoral immune responses in the tumor microenvironment." (PMID 38893120, 2024). "During the development of PDAC, the expression levels of the maturation marker MHC-II and the co-stimulatory molecules CD40 and CD86 on tumor-associated DCs decrease, which can be attributed to an increase in IL-6,150 of which M2-like TAMs are an important source." (PMID 40458305, 2024).
tumor (continued). "Furthermore, in the context of tumor-associated macrophages, we observed an elevated level of CD86 expression in the presence of E. coli within the OT-I group, compared to the OT-I group alone." (PMID 39572541, 2024). "Co-receptors CD80 (B7-1) and CD86 (B7-2) that are expressed on antigen-presenting cells (APCs) are also receptors of AdV3, allowing for the possibility of AdV3s to infect APCs and provide the tumor-associated antigens directly (if modified to do so)." (PMID 39309012, 2024). "In addition to upregulation of CTLA-4 and PD-1 on tumor-infiltrated T cells, in many tumors, the CD28 ligands CD80 and CD86 are poorly expressed both on tumor cells and tumor-associated myeloid cells." (PMID 35379805, 2022). "Moreover, CD80+ and CD86+ dendritic cells present in peritumoral tissues of NSCLC patients were associated with an immature phenotype that favors tumor immune escape." (PMID 35688943, 2022). "Additionally, GPC3, one of the tumor-associated antigens, elevated F4/80 + CD86+ macrophage (M1) percentage within tumor, in the meantime of inducing CD8+ T cell immune response specific to GPC3." (PMID 34112138, 2021). "In addition, α2,3 sialylated dendrimers reduced the expression of HLA-DR and CD86, markers associated with the anti-tumour M1 phenotype of macrophages." (PMID 33627655, 2021). "In a preclinical study, Wu and colleagues highlighted the immunomodulatory effects of PRRT in the murine xenograft model of human NETs, demonstrating that PRRT causes increased infiltration of CD86+ antigen presenting cells and natural killer cells into tumor tissue." (PMID 33809226, 2021). "For instance, IL-10 production by Treg cells decreases the interferon (IFN)-γ-dependent activation of antigen presenting cells (APCs), suppresses IFN-γ production in CD8+ cells and induces downregulation of major histocompatibility complex (MHC) II and CD86 in tumor-associated macrophages." (PMID 34539668, 2021). "Similarly, standard markers of macrophage phenotype (CD206 and CD86) assessed by immunofluorescence revealed greater heterogeneity in dermal macrophages compared to tumor-associated macrophages." (PMID 33959597, 2021). "Interestingly, higher proportions of tumor‐infiltrating CD40+ or CD86+ pDCs were linked to longer PFS, whereas higher proportions of tumor‐infiltrating CD80+ cDC2s or pDCs foresaw worse clinical outcome as it was linked with shorter PFS." (PMID 33282290, 2020). "Moreover, high expressions of CD80 or CD86 by tumor‐infiltrating pDCs after TLR stimulation were linked with a worse clinical outcome." (PMID 33282290, 2020). "In three CRC patients, low frequencies of CD86 expression on tumor-associated ILCs were observed, suggesting that ILCs may, under certain circumstances, acquire antigen-presenting characteristics in vivo." (PMID 32341343, 2020). "Subsequent studies have demonstrated that CTLA-4 is a molecular component expressed on certain tumor cell lines at various degrees of intensity and can cause apoptosis of CTLA-4-expressing tumor cells after interaction with soluble CD80 or CD86 recombinant ligands." (PMID 29672601, 2018). "However, lower infiltration of CD86+ TAMs was associated with aggressive tumor phenotypes, such as multiple tumor number (p = 0.006), high-grade TNM stage (p = 0.001) and elevated alaninetransaminase (ALT) (p = 0.020)." (PMID 26938527, 2016). "Induction of anti-tumor activity by M1-like macrophages after stimulation with LPS + IFN-γ was associated with a more activated phenotype as indicated by the up-regulation of CD86 and HLA-DR expression." (PMID 24612598, 2014). "Interestingly, concurrent loss of CD80/CD86 expression is found in CD58-deficient tumor cells." (PMID 39349829, 2024). "In tumor-draining lymph nodes (TDLNs), the proportion of CD86+CD11c+ DCs in the RCL@Pd@CuZ + RT group was 59.24% ± 1.21%, which was markedly higher than that in the RT group (43.14% ± 1.63%)." (PMID 41424843, 2026).
tumor (continued). "We therefore examined surface expression of MHC-I and the co-activating molecule CD86 on resident and migratory cDCs in the tumor-draining lymph nodes of metastasis-bearing mice." (PMID 40991399, 2026). "ALX301 treated mice demonstrated increased MHC-II expression on dendritic cells within the tumor and upregulation of CD86 co-stimulatory molecule on dendritic cells within the tumor, sentinel lymph nodes, and contralateral lymph nodes." (PMID 41701713, 2026). "Remarkably, the EGFR mutant tumor cells products reduced the expression of HLA‐DR, CD86, and CD80 on DCs compared to WT cells (all p < 0.05), although they did not significantly alter the phagocytic ability of DCs." (PMID 41144813, 2026). "Here we identify syntaxin 11 as a key regulator that enhances the expression of MHC I and co-stimulatory molecules CD80/CD86 on tumour cell membranes, enabling cancer cells to acquire dendritic-cell-like features." (PMID 41612046, 2026). "Experimental murine models indicated that the delivery of exosomal miR-32-5p was a strong tumor suppressor and disseminator, increased the recruitments of CD86 + antigen-presenting cells and CD8 + T lymphocytes, and boosted anti-neoplastic immunity." (PMID 41608526, 2026). "APS reduced tumour volume dose-dependently, with a 50% reduction at 200 mg/kg, increased M1 macrophages (CD86+), and decreased M2 macrophages (CD206+), indicating that APS reshape the tumour immune microenvironment by inhibiting M2 polarisation." (PMID 40649307, 2025). "Profiling of the activation states revealed that the immune cells had not only infiltrated the tumour site but were also activated CD86, corroborating the in vitro results." (PMID 40592827, 2025). "While we would anticipate that CD80 and CD86 would have a positive impact on anti-tumor immunity, we demonstrate that blockade of CD80 and CD86 signaling limits CD4 infiltrates in tumors and prevents the Treg expansion caused by radiation treatment." (PMID 41417245, 2025). "In contrast, certain treatments can elevate CD86 levels, which promote the anti‐tumor response via activating effector T cells." (PMID 40635602, 2025). "The mean histoscore for CD86 (M1 macrophage marker) was significantly higher in DLBCL samples than in non-tumor controls (5.4 ± 1.1 vs 3.4 ± 1.0, p = 9.0e-08) as well as the mean CD86+ cell percentage (74.6% ± 17.8 vs 27.9% ± 7.8, p = 4.0e-24)." (PMID 41415285, 2025). "The changes of M1 macrophages which stained with F4/80, Cd11b and CD86 in tumor tissues, peripheral blood and spleen were detected." (PMID 40394236, 2025). "Intratumoral delivery of rM-FC effectively recruits and activates dendritic cells (DCs), especially CD103+ DCs and CD80+CD86+ DCs, further inducing sufficient migration of effector memory T cells into the tumor microenvironment." (PMID 39780958, 2025). "This approach decreased the number of TIM-1+ B cells in the tumor and shifted B cells to higher expression of CD86 and MHC class II, enhancing the antigen presentation capability and further boosting the antitumor efficacy of CD8+ cytotoxic T cells." (PMID 40321752, 2025). "This process subsequently activated CD80+ CD86+ macrophages, thereby enhancing the presentation of tumor antigens." (PMID 41583493, 2025). "Our analysis revealed a significantly longer brain metastasis survival (BMS) in patients with high CD86 expression in the tumor nest of brain metastases, showing a 63.6% increase in median survival (p = 0.036)." (PMID 40510346, 2025). "CD86 + memory B cells can promote tumor proliferation and immune evasion via the CD46-JAG1 signaling pathway while also being associated with antitumor immune responses." (PMID 40158161, 2025). "LBP-CD155L NVs reduce immunosuppressive cells in the tumor microenvironment, such as MDSCs and Tregs, while enhancing CD86 level and promoting effector T cell infiltration." (PMID 41050703, 2025). "Akt inhibitor increased the proportion of CD86+ DCs among total DCs in the primary tumor compared to the control." (PMID 41378083, 2025).
tumor (continued). "IF analysis of these tumor tissues indicated that HO-1 inhibition combined with Doc significantly increased the number of M1 phenotype macrophages, represented by F4/80+ and CD86+ cells, compared to each treatment alone and the control group (P < 0.05)." (PMID 40037158, 2025). "Tumor co-culture induced further enhancement of M1-associated markers including CD80/CD86, MHC-II and IL-1β/IL-6/TNF-α/IL-12/IFN-γ, while suppressing M2 markers CD163/CD206, indicating tumor-triggered M1 polarization." (PMID 41388305, 2025). "Complementary in vivo assays substantiate that RP-6306, either as monotherapy or in synergy with gemcitabine, significantly escalates CD86 levels while diminishing CD163 expression in tumor matrices." (PMID 40664640, 2025). "Following F1F3 stimulation, both HeLa and KHDRBS1 KO HeLa tumours showed strong upregulation of iNOS (inducible nitric oxide synthase) and CD86, canonical markers of M1 macrophages with pro-inflammatory and antitumour." (PMID 40738927, 2025). "We also examined the mature DC subtype, the CD45+CD3e−MHCII+CD86+CD11c+ cells in the tumor draining lymph nodes." (PMID 39871312, 2025). "In this study, we evaluated the levels of CD80 and CD86 in tumor tissues and observed an upregulation in the miR-497-NBs+US and miR-497/SK-NBs+US treatment groups." (PMID 41583493, 2025). "Adding chemotherapy to innate agonists enhances the infiltration of dendritic cells (DCs) in the tumors and CD86+ mature DCs in tumor draining lymph nodes." (PMID 39871312, 2025). "Comparing gene expression in the immune cell infiltrate between the two primary tumours, the greatest number of DEGs was seen in the macrophage (CD86 and MS4A7-expressing) cluster." (PMID 40438247, 2025). "We found that the intra-T/peri-T ratio of CD86+ cells was significantly lower in CD68+ (pan-macrophage marker) cells than CD20+ tumor B cells (0.4 ± 0.1 vs 1.4 ± 0.4, p = 3e-13)." (PMID 41415285, 2025). "Decreased anti-tumor immune responses in the tumor microenvironment have been associated with the CTLA-4/CD80,CD86 axis between immune cells and tumoral cells (Derakhshani, Hashemzadeh, Asadzadeh, and Shadbad 2021)." (PMID 39905036, 2025). "Splenic CD80+/CD86+ DC populations increased markedly, correlating with expanded tumor-infiltrating CD8+ T cells." (PMID 40892295, 2025). "M1 macrophages (CD86+CD80+) are critical for suppressing tumor growth, while M2 macrophages (CD206+CD163+) display protumor properties." (PMID 39774471, 2025). "As a result, the combination therapy was associated with the increased infiltration of CD8+ T lymphocytes, CD86+-activated monocytic myeloid-derived suppressor cells, and TAMs, ultimately contributing to a robust anti-tumor immune response." (PMID 40725216, 2025). "Cytokines such as Il12, Ciita, Cd86, Tnfα are well-known for their role in promoting T cells mediated anti-tumour immune response." (PMID 40316725, 2025). "In agreement, CD86+ cell count was significantly higher in the macrophage (CD68+) than in the tumor cell (CD20+) compartment (282.0 ± 63.4 vs 238.1 ± 64.3, p = 0.02)." (PMID 41415285, 2025). "A later component of the leukemia treatment, cytosine arabinoside (Ara‐C), which stops the cell cycle and tumor cell division, more than doubled the CD86 levels in 50% of cases." (PMID 40635602, 2025). "At the same time, consistent results were observed in the GSK3B-IN groups in that GSK3B downregulation mediated macrophage M1 polarization (CD86 marker) in tumor cells." (PMID 40548257, 2025). "In CCH, CD80 showed a declining expression, which is putatively related to tumor regression, while CD86 showed comparable levels." (PMID 40271486, 2025). "In the balb/c model, NCTD markedly reduced tumor cell density and differentiation in mice along with increased CD86 expression." (PMID 40394236, 2025). "In contrast, the fraction of CD163+CD86+ M2-like macrophages was significantly increased in all 4 of 4 tumor entities compared to that seen in NMC aspirates." (PMID 40274631, 2025).